TLR4 (toll like receptor 4)
Diseases named in the same sentence as TLR4 in open-access papers (continued):
Sharing a sentence is not in itself a finding about the gene and the disease.
depression (continued). "In summary, we found that n‐3 PUFAs was able to improve the depressive behavior and hippocampal neuroinflammation in mice with depression, the mechanism of which may be achieved by regulating TLR4 pathway." (PMID 36301036, 2022). "Previous studies have found that safflower extract could improve depression in mice by inhibiting TLR4/NLRP3 inflammatory signaling pathway." (PMID 36301036, 2022). "Taken together, TLR4 activation could reverse the inhibitory effect of n‐3 PUFAs on depression‐like behavior of the mice." (PMID 36301036, 2022). "The effects of S100A9 protein were attenuated by TLR4 inhibitor TAK-242, indicating that the dysfunction of S100A9/TLR4 signaling in the hippocampus could generate neuroinflammation and depression-like behaviors." (PMID 35814253, 2022). "In this study, DHA was used to supplement n‐3 PUFAs and it was observed that n‐3 PUFAs could improve the depression‐like behavior and inflammatory response in depression mice by inhibiting TLR4 expression." (PMID 36301036, 2022). "Studies have also shown that adipose-derived MSCs protect mice from chronic mild stress-induced depression-like behaviors by modulating Nrf2/HO-1 and TLR4/NF-κB signaling pathways, therefore, the role of MSCs in the treatment of cognitive impairment in MDD is also anticipated." (PMID 36406755, 2022). "To verify whether EA treatment modulates this molecular signaling mechanism, we detected and quantified the TLR-4/NF-κB and MAPK and NLRP3 inflammasomes, which is a risk factor of depression." (PMID 35087621, 2022). "Both acute and chronic stress could activate the peripheral or central TLR4 signaling pathway in rodents and induce depression‐like behaviors." (PMID 36301036, 2022). "In our study, it was found that n‐3 PUFAs was able to improve depression by regulating TLR4." (PMID 36301036, 2022). "The Traditional Chinese Medicine Systems Pharmacology Database (TCMSP), the Analysis Platform, DrugBank, and other databases were analyzed using data mining, and the results show that the active components of HP and depression are linked to targets such as TNF-, IL-2, TLR4, and so on." (PMID 36556951, 2022). "Following antidepressant treatment, the depressive symptoms improved and also the levels of TLR4 significantly decreased, further indicating that TLR4 might be correlated with the pathology of depression." (PMID 34526897, 2021). "However, there are no studies which focus on the treatment of depression based on the TLR4-mediated inflammatory damages in HFD/CUMS-induced depression-like animal models." (PMID 34975477, 2021). "In addition, toll-like receptors (TLRs) are also involved in the pathogenesis of depression, especially the activation of TLR4 in the brain." (PMID 34079622, 2021). "Importantly, TLR-4 activation induces depressive-like behaviors in animal models, and it has been proposed as a crucial factor in the inflammatory theory of depression." (PMID 34934041, 2021). "It has been proposed that neuroinflammation-related activation of TLR4/Myd88/NF-κB signaling pathway in the hippocampus might play an important role in partially mediating LPS-induced depression-like behaviors." (PMID 34299230, 2021). "Three types of PRRs have been identified, namely, Toll-like receptors (TLRs), NOD-like receptors (NLRs), and C-type lectin receptors (CLRs); of these, TLR4 and the inflammasome-associated NOD-like receptor pyrin domain containing 3 (NLRP3) are most closely linked to depression." (PMID 33505499, 2021). "This study reports an inverse correlation between methylation of TLR4 and severity of depressive symptoms in a cohort of young adult women seeking psychiatric care mainly for symptoms of unipolar depression and/or anxiety, and this finding was replicated in a cohort of young adult twins." (PMID 34226490, 2021). "Further studies showed that the role of TLR4 in depression may be related to the interaction between TLR4 and the hypothalamus-pituitary-adrenal cortex (HPA) axis." (PMID 34526897, 2021).
depression (continued). "As the primary action of the GG constituent glycyrrhizin is to inhibit 11betaHSD2 and (directly or indirectly) TLR4, this principal may emerge as a new target for a definable subgroup of patients with depression, if confirmed in future research." (PMID 33362613, 2020). "The TLR4-specific inhibitor Cli-095 markedly inhibited the upregulation of TLR4 in the hippocampus and prefrontal cortex, and improved chronic unpredictable mild stress-induced depression-like behaviors in mice." (PMID 32317989, 2020). "The TLR4 signaling pathway may be a potential target for the anti-inflammatory treatment of depression." (PMID 32317989, 2020). "The activation of TLR4 is involved in the pathophysiological process of depression." (PMID 32328132, 2020). "Interestingly, TLR4 expression correlates with depression in humans and followed anxiety and depressive-like behavior in mice fed a high-cholesterol diet." (PMID 30837902, 2019). "These outcomes suggest an essential role of TLR4 in the pathogenesis of depression." (PMID 31139084, 2019). "Recently, a growing body of evidence indicates that TLR3 and TLR4 may be involved in psychosis with immune dysfunction including major depressive disorders and BD." (PMID 31379619, 2019). "Additionally, increased expression of a variety of innate immune genes and proteins, including IL-1β, IL-6, TNF, Toll-like receptor 3 (TLR3) and TLR4, has been found in post-mortem brain samples from individuals with depression that died by suicide." (PMID 31647818, 2019). "A growing body of evidence shows that TLR4 pathway may be an important link between inflammation and depression." (PMID 31139084, 2019). "The authors suggest that TLR4-mediated mechanisms could underpin the neural, immune, and neuroendocrine alterations seen in patients with major depressive disorder." (PMID 26082681, 2015). "We speculate that its role in TLR4 signaling may link it to the neuroinflammation and depression induced by treatment with lipopolysaccharide." (PMID 23597049, 2013). "TLR4-NF-κB/NLRP3/ IL-1β pathway may be a key signaling pathway in depression." (PMID 38459460, 2024). "The present study provided evidence that acupuncture exerted potential preventive effect that might be mediated in part by suppressing the neuroinflammation induced by TLR4 signaling pathway, which may be a promising treatment target to improve current treatments for depression." (PMID 37917302, 2024). "Therefore, the changes in these TLR4-regulating miRNAs in MDD patients and their association with depression severity and their responsiveness to AD treatment could be used as biomarkers in diagnosis and treatment response." (PMID 36902096, 2023). "Therefore, it can be confirmed that TLR4 is involved in the process of depression, and KJG may be used as an effective anti-depressant medication." (PMID 37173696, 2023). "Additionally, it was found that LPS could set off the innate immune system via TLR4 signaling pathway and induce pathological behaviors among animal models, which is similar to the symptoms of depression among humankind in animal experiments." (PMID 36301036, 2022). "n‐3 PUFAs may ameliorate depression‐like behaviors via reducing hippocampal neuroinflammation in CUMS‐induced mice by regulating TLR4 expression, suggesting that n‐3 PUFAs may be an effective antidepressant, which provides evidence for future treatment of depression." (PMID 36301036, 2022). "Notably, evidence points to the TLR4-MyD88/NF-κB signaling pathway as playing a key role in the immune response by affecting microglial state, leading to increased chronic low-grade inflammation and depression-like behaviors." (PMID 35370734, 2022). "Moreover, the anti‐depressant activity of n‐3 PUFAs is mediated by inhibition of TLR4, suggesting n‐3 PUFAs or TLR4 control may be a therapeutic strategy for depression." (PMID 36301036, 2022). "Therefore, modulation of the TLR4 signaling pathway may be one of the most effective strategies to combat depression." (PMID 35923544, 2022).
depression (continued). "The release of inflammatory cytokines mediated by TLR4/NLRP3 inflammasome signaling-induced immunoinflammatory activation may represent a common pathogenic process underlying the development of gastrointestinal diseases and depression." (PMID 33505499, 2021). "In summary, the release of inflammatory cytokines mediated by TLR4/NLRP3 inflammasome signaling pathway-induced immunoinflammation may represent a common pathogenic mechanism underlying the development of gastrointestinal diseases and depression." (PMID 33505499, 2021). "Thus, the link between TLR4 and symptoms of depression should be further investigated, and TLR4 may be a potential therapeutic target for the development of antidepressants." (PMID 34975477, 2021). "It has not been reported whether there is a differential expression of miR-223 in the negative feedback intervention of signal pathway factors such as TLR4, especially whether this mechanism of action is involved in the process of the inflammatory response in the hippocampus of depression." (PMID 32295141, 2020). "Moreover, a recent clinical study has shown that the mRNA transcription of TNFAIP3, a suppressor of the TLR4 pathway, was inversely correlated with severity of depression and effectively predicted response to antidepressant treatment in major depressive disorder." (PMID 31139084, 2019). "Therefore, the present investigation was to estimate whether BA treatment possessed the antidepressant-like effects on CUMS induced depression by inhibiting inflammation through down-regulation of HMGB1/TLR4/NF-κB signaling pathway." (PMID 30658416, 2019). "The activation of TLR4 could trigger neuroinflammation and evoke depression-like behaviors." (PMID 31068207, 2019). "preclinical studies have shown that Yangxin decoction alleviates depression-like behaviors in CUMS-induced rats, potentially by inhibiting hippocampal neuronal apoptosis and inflammatory responses via the TLR4/NLRP3 signaling pathway." (PMID 41189264, 2025). "Quinoa saponin shows potential as a natural dietary supplement for the treatment and prevention of anxiety and depression by regulating the MGB axis and inhibiting the activation of the TLR4/MyD88/NF-κB pathway." (PMID 40936908, 2025). "TLR4 and NF-κB, important regulators of NLRP3-complex priming, were also increased, which further confirmed the inflammation condition in atria of depression." (PMID 38261756, 2024). "CRF receptor subtype 1 (CRF1), CRF2, and TLR4 were found to be upregulated in peripheral blood samples of IBS patients, especially in patients with concomitant depression." (PMID 39749341, 2024). "TLRs, especially TLR2 and TLR4, were found to participate in neurodegenerative diseases such as AD, PD, and ALS, as well as in neuropsychiatric diseases such as depression." (PMID 39408923, 2024). "Alirocumab, an inhibitor of PCSK9 which is a protein correlated to TLR4 regulation, prevented CUMS-induced depression-like-behaviors in Wistar rats." (PMID 38791125, 2024). "TLR4 and TLR2 were upregulated in peripheral blood samples of IBS patients, especially in IBS patients with depression." (PMID 39749341, 2024). "Inhibited elevated levels of pro-inflammatory factors in the brains of stressed mice via the TLR4/p38 MAPK pathway and alleviates depression-like behavior." (PMID 37962460, 2024). "Upregulation of miR‐144‐5p in the DG ameliorated depression‐like behavior in CUS mice and attenuated neuronal abnormalities by directly targeting PTEN and TLR4 expression." (PMID 37308778, 2023). "This review summarizes the pharmacological regulations of natural products from TCM in the prevention and treatment of depression from the aspects of transcription factors (CREB, NF-κB, Nrf2) and molecular signaling pathways (BDNF-TrkB, MAPK, GSK-3β, TLR-4)." (PMID 35923544, 2022).
depression (continued). "Arctigenin exhibits significant antidepressant effects in rodent models of depression, attenuates microglial activation and neuroinflammation through HMGB1/TLR4/NF-κB and TNF-α/TNFR1/NF-κB signaling pathways, and inhibits IDO increase and decrease in 5-HT." (PMID 36388178, 2022). "The possible mechanism is to increase activation of astrocytes in the hippocampus through the Pg-LPS/TLR4 signaling pathway, leading to downregulating astrocyte p75NTR and inhibiting BDNF maturation and, ultimately, depression." (PMID 36440396, 2022). "Our results showed that the expression levels of TLR4, MyD88, NF-κB-p65, TAK1, IRAK1, TRAF6, inflammasome-related NLRP3, ASC, and caspase-1 were all increased in rats of the depression model group." (PMID 33505499, 2021). "The TLR4 signaling pathway and the NLRP3 inflammasome are closely related to depression and inflammatory bowel disease." (PMID 33505499, 2021). "In order to identify the intracellular mechanism responsible for the antidepressant effect of BA in CUMS induced depression, the protein expressions of BA on HMGB1, TLR4, p-NF-κB, NF-κB in the hippocampus were investigated." (PMID 30658416, 2019). "In conclusion, the present study confirmed that BA possessed efficient antidepressant effects on depression, which was possibly related to the inhibition of HMGB1/TLR4/NF-κB pathways." (PMID 30658416, 2019). "The present study shows that TLR2 and TLR4 mRNAs in DP-IBS patients are higher than in the control group, which indicates that TLR participates in the inflammation reaction in IBS and depression." (PMID 27478433, 2016). "Escin, a natural triterpenoid saponin from Aesculus chinensis (Suoluozi), alleviates CUMS-induced depression-like behaviors by modulating both the BDNF/TrkB/CREB and Toll-like receptor 4 (TLR4)/Myeloid differentiation factor 88 (MyD88)/NF-κB signaling pathways." (PMID 40936908, 2025). "They further found that OBB or OBB‐NC administration can reduce long‐term neuropsychiatric complications such as anxiety, depression, and cognitive impairment, as well as inhibit the HMGB1‐mediated TLR4/NF‐κB pathway in microglia by downregulating the levels of TLR4, HMGB1, NF‐κB, TNF‐α and IL‐6." (PMID 40824273, 2025). "Altogether, these results indicate that AKK improves microglial activation through inhibiting the TLR4/NF-κB inflammatory pathway by producing PA, which may contribute to the protective effects of PA on ARDS-related depression." (PMID 40110391, 2025). "In addition, the expression levels of TLR4, P65, P-P65, NLRP3, ASC, caspase-1, and IL-1β were elevated in depression models." (PMID 38261756, 2024). "Additionally, TLR4 knockout mice exhibited pronounced depression-like behavior, while TLR2 knockout mice showed significant impairment in recovery from depression in the male mice." (PMID 39408923, 2024). "Overall, the findings suggest that KJG may have therapeutic potential for depression by targeting the PI3K/AKT/FOXO1 pathway and its potential regulation by TLR4." (PMID 37173696, 2023). "However, the therapeutic effect of SSB2 on depression is blocked when GPX4 is knocked out, indicating that SSB2 acts through a GPX4-dependent manner in mediating TLR4/NF-κB pathway, exerting its anti-ferroptosis and anti-neuroinflammatory roles." (PMID 38259274, 2023). "It is suggested that muscone may alleviate IL-1β-related CNS inflammation through TLR4/MyD88 and TLR4/NLRP3 pathways, thereby attenuating LPS-induced depression-like behaviors." (PMID 35923544, 2022). "TLR4, a member of the TLR family, has been found in a growing number of studies that inhibition of TLR4 or related signaling pathways could improve depression even the occurrence of depression." (PMID 36301036, 2022). "The mouse model of depression was established through chronic unpredictable mild stress (CUMS), the mice were intervened with n‐3 PUFAs, and then the expression of toll‐like receptor 4 (TLR4) was stimulated with lipopolysaccharides (LPS)." (PMID 36301036, 2022).
depression (continued). "TLR4 overexpression on monocytes has been found in different noninfectious diseases, such as atrial fibrillation and major depression." (PMID 33451043, 2021). "We found that Cnr2 and Tlr4 genes related to neuroinflammation were robustly upregulated in the ACC and amygdala of aging mice, suggesting that these two genes play an important role in the genesis of depression and anxiety during aging." (PMID 33015035, 2020). "The mRNA expression of TLR3 and TLR4 has been found to increase in the prefrontal cortical regions of individuals with depression that died by suicide and depressed non-suicide subjects." (PMID 31647818, 2019). "CRF1, CRF2, TLR2, and TLR4 in IBS patients with depression are significantly higher than those without depression and controls." (PMID 27478433, 2016). "However, the mechanism of the preventive effect of acupuncture for depression through modulating the stress-induced activation of neuroinflammation mediated by TLR4 signaling pathway has not been fully elucidated." (PMID 37917302, 2024). "Moreover, various proinflammatory cytokines and chemokines derived from TLR4 and TLR7 activation are now recognized as potential markers of psychiatric conditions, including depression, postpartum depression, post-traumatic stress disorders and alcohol use disorders." (PMID 35967446, 2022). "For example, TNF, TLR4, IL-2, BCL-2, etc., are closely related to inflammation, and these targets may be the key targets of Hyp, the main active component of HP, in the treatment of depression." (PMID 36556951, 2022). "Moreover, suicide victims with depression showed higher levels of IL-1β, IL-6 and TNF in postmortem brains, while the receptors for the production of these cytokines, such as Toll-like receptor 3 (TLR3) and TLR4, were also affected." (PMID 34827513, 2021). "Several reports have supported the notion that inhibiting cytokine release and/or interrupting the TLR4/Myd88/NF-κB signaling pathway may be effective in reducing the magnitude of LPS-induced depression-like behavior, but not LPS-induced sickness." (PMID 34299230, 2021). "However, there have been no reports of using puerarin for the treatment of depression based on Toll-like receptor 4 (TLR4)–mediated inflammatory injury." (PMID 34975477, 2021). "The pattern receptor gene, TLR4, involved in the innate immune system, has been shown to be up-regulated in the PFC of schizophrenia subjects, as well as in the blood of individuals with major depressive disorder, and peripheral T cells of children with autism." (PMID 33276438, 2020).